VAT1 (vesicle amine transport 1)
Description:
Multifunctional protein with enzymatic and transport activities. Probable NADPH-dependent quinone oxidoreductase which physiological substrates and function are unclear. Alternatively, has also been suggested to mediate the transfer of negatively charged phospholipids including phosphatidic acid (PA), phosphatidylserine (PS) and phosphatidylglycerol (PG) between endoplasmic reticulum and mitochondrial membranes. Could regulate mitochondrial fusion through its interaction with mitofusins.
Synonyms: MIB; VAT-1; VATI; FLJ20230
Tractability: Small molecule: a structure with a bound ligand is known. Antibody: its Gene Ontology location is reachable by antibodies, with high confidence; UniProt places it where antibodies can reach, with medium confidence. PROTAC: ubiquitination databases record sites on it; its protein half-life has been measured; a small molecule that binds it is known.
Target class: Enzyme; Oxidoreductase
Gene: Protein-coding gene on chromosome 17 (43,010,692 to 43,025,123, reverse strand). Ensembl gene ENSG00000108828.
Subcellular location: Cytoplasm, cytosol; Mitochondrion outer membrane
Pathways (Reactome):
Immune System: Neutrophil degranulation
Gene Ontology:
Molecular function: NADPH dehydrogenase (quinone) activity; phospholipid transfer activity; protein binding; quinone reductase (NADPH) activity; oxidoreductase activity; zinc ion binding
Biological process: intermembrane phospholipid transfer; negative regulation of mitochondrial fusion
Cellular component: cytoplasm; cytosol; extracellular exosome; azurophil granule lumen; extracellular region; mitochondrial outer membrane
Genetic constraint (gnomAD): Loss-of-function variants: 24 observed, 33.1 expected, observed/expected ratio (o/e) 0.73, 90% interval 0.52 to 1.02. The upper end of that interval is the gene's LOEUF score, 1.02, which puts it in group 4 of 6, group 1 being the genes least tolerant of losing a copy. Missense variants: 436 observed, 532.87 expected, observed/expected ratio (o/e) 0.82, 90% interval 0.76 to 0.89. Synonymous variants: 212 observed, 219.69 expected, observed/expected ratio (o/e) 0.96, 90% interval 0.86 to 1.08.
Homologues: Orthologues: chimpanzee VAT1 (98% identical), macaque VAT1 (96% identical), dog VAT1 (93% identical), pig VAT1 (90% identical), rat Vat1 (90% identical), mouse Vat1 (90% identical), guinea pig VAT1 (76% identical), tropical clawed frog vat1 (62% identical), zebrafish vat1 (62% identical), Caenorhabditis elegans D2063.1 (20% identical), Caenorhabditis elegans sodh-2 (19% identical), Caenorhabditis elegans adh-1 (18% identical), and 2 more. Paralogues in human: VAT1L (43% identical), PTGR3 (26% identical), CRYZ (26% identical), TP53I3 (26% identical), MECR (23% identical), RTN4IP1 (21% identical), ADH1A (20% identical), ADH1B (20% identical), ADH1C (20% identical), ADH5 (19% identical), SORD (19% identical), CRYZL1 (19% identical), and 5 more.
Diseases named in the same sentence as VAT1 in open-access papers:
VAT1 is named in the same sentence as 13 diseases in open-access papers, as found by Europe PMC text mining. Sharing a sentence is not in itself a finding about the gene and the disease. The quoted sentences say what the papers report.
schizophrenia (2 papers, 2017 to 2025). A major psychotic disorder characterized by abnormalities in the perception or expression of reality. "The synaptic vesicle membrane protein VAT‐1 homolog‐like (VAT1L) has been associated with schizophrenia and VAT1, its paralog, is responsible for the storage and release of neurotransmitters in synapses and its activity in keratinocytes is calcium‐dependent." (PMID 39910963, 2025). "These include: VAT‐1, DAD‐1, PAQR9, BCKD, BDH, Prickle4, PP2A, RPL13A, SPRED2, KLP, FAM36A, NAB1, CLSTN3, PEDF‐R, and FZD3 (Frizzled gene previously associated with different psychopathologies, most notably Schizophrenia)." (PMID 27696737, 2017).
glioma (1 paper, 2025). A benign or malignant brain and spinal cord tumor that arises from glial cells (astrocytes, oligodendrocytes, ependymal cells). "Based on the Lasso regression analysis, five-gene signature was established which was associated with VAT1-related radioresistance in gliomas." (PMID 40034328, 2025). "Vesicle amino transport protein 1 (VAT1), localizing in cytoplasm and mitochondria, was identified as potential prognostic factor in patients with glioma." (PMID 40034328, 2025). "Previously, we identified that the high expression of VAT1, as a prognostic marker of gliomas, promoted the generation of tumor immunosuppressive microenvironment." (PMID 40034328, 2025). "Moreover, we previously found the positive correlation between VAT1 expression and some immune checkpoints and verified in vitro assays, indicating the immunosuppressive function of VAT1 in gliomas." (PMID 40034328, 2025).
liver fibrosis (1 paper, 2021). "Importantly, we found that lysosomal DEPs, including CTSB/D/Z, LIPA, DPP7 and GLMP, and mitocondrial DEPs, AKR1B10, and VAT1 had been connected with liver fibrosis, damage, and steatosis in previous studies, validiting our dataset." (PMID 34440927, 2021).
Parkinson disease (1 paper, 2019). A progressive degenerative disorder of the central nervous system characterized by loss of dopamine producing neurons in the substantia nigra and the presence of Lewy bodies in the substantia nigra and locus coeruleus. "In the present study, we also detected that five DEmRNAs, including COX7B2, UBA1Y, VAT1, CYCT and SLC6A3, were enriched in the pathway of Parkinson’s disease." (PMID 31447646, 2019).
sarcoidosis (1 paper, 2025). Sarcoidosis is a multisystemic disorder of unknown cause characterized by the formation of immune granulomas in involved organs. "However, upregulation of SPP1 was more modest, and unlike NL and NXG macrophages, sarcoidosis lesional macrophages strongly overexpressed APOE, VAT1, TLR8, and ALDH1A1 among other genes." (PMID 39989459, 2025).
Varicose veins (1 paper, 2023). Enlarged and tortuous veins. "We identified eight plasma proteins that are significantly associated with the risk of varicose veins after Bonferroni correction (P < 2.495 × 10−5), with five being protective (LUM, POSTN, RPN1, RSPO3, and VAT1) and three harmful (COLEC11, IRF3, and SARS2)." (PMID 37404740, 2023). "As a result, eight proteins were found to be causally associated with varicose veins, including COLEC11, IRF3, LUM, POSTN, RPN1, RSPO3, SARS2, and VAT1." (PMID 37404740, 2023). "However, none of the other identified pleiotropy could completely explain the association with varicose veins, including RPN1, RSPO3, and VAT1." (PMID 37404740, 2023).
cancer (5 papers, 2020 to 2025). A tumor composed of atypical neoplastic, often pleomorphic cells that invade other tissues. "The involvement of VAT1, a largely uncharacterized enzyme, has also been reported in the regulation of cancer cell motility and its interaction with Talin-1, a key cytoskeletal protein." (PMID 32867073, 2020). "Neocarzilin A was a class of natural products containing trichloromethyl ketone and could be served as an effective inhibitor for targeting the VAT-1 pathway to control cancer cell movement." (PMID 40431174, 2025). "Moreover, a recent study indicated that a natural polyenone, neocarzilin A (NCA), produced by Streptomyces carzinostaticus, functions as a potent inhibitor of cancer cell motility by targeting VAT-1-controlled pathways." (PMID 33483563, 2021). "It has also been proposed that VAT-1 plays a role in cancer cell motility." (PMID 33483563, 2021).
gynecological tumor (1 paper, 2017). "Genes that highly expressed in EAEMT compared with EA type cells were TCEAL4, BAG1, VAT1, and GPI which are known to be gynecological tumor markers." (PMID 29079795, 2017).
VAT1 also shares sentences with these, for which no sentence is quoted: tumor (3 papers); cognitive decline (1); hemangioendothelioma (1); neurodegenerative disease (1); steatosis (1).